TRNAU1AP (tRNA selenocysteine 1 associated protein 1)
Description:
Involved in the early steps of selenocysteine biosynthesis and tRNA(Sec) charging to the later steps resulting in the cotranslational incorporation of selenocysteine into selenoproteins. Stabilizes the SECISBP2, EEFSEC and tRNA(Sec) complex. May be involved in the methylation of tRNA(Sec). Enhances efficiency of selenoproteins synthesis.
Synonyms: SECP43; TRSPAP1; FLJ20503; PRO1902
Tractability: PROTAC: ubiquitination databases record sites on it.
Gene: Protein-coding gene on chromosome 1 (28,553,001 to 28,578,545, forward strand). Ensembl gene ENSG00000180098.
Subcellular location: Nucleus; Cytoplasm
Subcellular location (Human Protein Atlas): Nucleoplasm; Cytosol
Gene Ontology:
Molecular function: protein binding; RNA binding; tRNA binding; nucleic acid binding
Biological process: selenocysteine incorporation
Cellular component: cytoplasm; nucleus
Genetic constraint (gnomAD): Loss-of-function variants: 31 observed, 44.41 expected, observed/expected ratio (o/e) 0.7, 90% interval 0.52 to 0.94. The upper end of that interval is the gene's LOEUF score, 0.94, which puts it in group 4 of 6, group 1 being the genes least tolerant of losing a copy. Missense variants: 287 observed, 372.33 expected, observed/expected ratio (o/e) 0.77, 90% interval 0.7 to 0.85. Synonymous variants: 142 observed, 133.88 expected, observed/expected ratio (o/e) 1.06, 90% interval 0.93 to 1.22.
Homologues: Orthologues: pig TRNAU1AP (100% identical), dog TRNAU1AP (99% identical), macaque TRNAU1AP (99% identical), guinea pig TRNAU1AP (99% identical), rat Trnau1ap (99% identical), mouse Trnau1ap (99% identical), chimpanzee TRNAU1AP (77% identical), zebrafish trnau1apa (53% identical), Drosophila melanogaster Secp43 (44% identical), tropical clawed frog trnau1ap (43% identical), Caenorhabditis elegans T07F10.3 (29% identical). Paralogues in human: HNRNPDL (24% identical), TIA1 (23% identical), HNRNPD (23% identical), TIAL1 (23% identical), HNRNPA3 (22% identical), HNRNPAB (22% identical), HNRNPA2B1 (22% identical), HNRNPA1 (21% identical), HNRNPA1L2 (21% identical), HNRNPA1L3 (21% identical), RBM4B (21% identical), MSI2 (20% identical), and 24 more.
Diseases named in the same sentence as TRNAU1AP in open-access papers:
TRNAU1AP is named in the same sentence as 3 diseases in open-access papers, as found by Europe PMC text mining. Sharing a sentence is not in itself a finding about the gene and the disease. The quoted sentences say what the papers report.
steatosis (1 paper, 2021). Increased lipid within the cytoplasm of cells. "Besides the selenoproteins GPX2, DIO1, and SEPHS2, the gene for TRNAU1AP also had higher expression in steatosis in the “selenium metabolism and selenoproteins” pathway, and TXNRD3 had lower expression in steatosis." (PMID 34869521, 2021).
cancer (1 paper, 2021). A tumor composed of atypical neoplastic, often pleomorphic cells that invade other tissues. "Tranu1ap (tRNA selenocysteine 1 associated protein 1) has been shown to inhibit proliferation in cancer cells by acting through the PI3K/AKT pathway." (PMID 34824385, 2021).
TRNAU1AP also shares sentences with these, for which no sentence is quoted: breast carcinoma (1 paper).